SOX4 (SRY-box transcription factor 4)
Diseases named in the same sentence as SOX4 in open-access papers (continued):
Sharing a sentence is not in itself a finding about the gene and the disease.
pancreatic cancer (continued). "Taken together, these results indicate that miR-30d/SOX4/PI3K-AKT axis suppresses the growth and invasion of pancreatic cancer cells in vivo." (PMID 33824274, 2021). "Our study demonstrated that dysregulation of the miR-30d/SOX4/PI3K-AKT axis promotes the development and progression of pancreatic cancer." (PMID 33824274, 2021). "Here we found that SOX4 activated the PI3K-AKT pathway to promote the tumorigenesis and metastasis of pancreatic cancer." (PMID 33824274, 2021). "While Id1 downregulation was deleterious to cells derived from pancreatic tumors that retained functional TGF-β pathway, they were protected from apoptosis when Id1 was dysregulated and SOX4 expression was decreased." (PMID 33126649, 2020). "Interestingly, a recent study showed that TGF-β could drive tumor suppression in pancreatic cancer cells which underwent a lethal epithelial-mesenchymal transition (EMT) by converting TGF-β-induced Sox4 from an enforcer of tumorigenesis into a promoter of apoptosis." (PMID 28903735, 2017). "Since the cooperation between SOX4 and KLF5 has been suggested as a molecular mechanism that drives tumorigenesis in SMAD4 defect pancreatic cancer cells, we postulated that Ep_VGLL1 represents cancer cells in SMAD4-deficient oncogenic processes driven by TGF-β." (PMID 38297291, 2024). "We examined the TCGA dataset and also found a negative expression correlation between SOX4 and miR-30d in pancreatic cancer tissues." (PMID 33824274, 2021). "We first mined the GEO datasets of pancreatic cancer and found that SOX4 was increased in tumor samples compared with matched non-tumor counterparts." (PMID 33824274, 2021). "As a result, we suggest that RAS/MEK/ERK signaling is not involved in the regulation of SOX4 expression in pancreatic cancer cells." (PMID 23251334, 2012). "An alternative could be other epigenetic modifications such as hypomethylation of the SOX4 gene, as exemplified by hypomethylated Claudin4, Lipocalin2, and S100A4, which accounts for their overexpression in pancreatic cancers." (PMID 23251334, 2012). "Interestingly, when pancreatic tumors mutate their Smad4 gene and thus lose its expression, TGFβ signaling fails to induce Snail1 or EMT, however, it can induce Sox4 expression; the coordinate action of Sox4 and the pre-existing KLF5 promotes tumorigenesis." (PMID 27367735, 2016). "The highly correlated expression of SOX4 with SEMA3/Plexin/NRP1 family members in human PanIN and PDAC suggests that SOX4 might function as a master transcription factor to drive the expression of SEMA3 and Plexin genes in pancreatic cancer formation." (PMID 23251334, 2012). "Collectively, these results suggest that SOX4 could function as a master factor to activate the transcription of SEMA3 and Plexin genes simultaneously, leading to the expression of multiple SEMA3 and Plexin family members in pancreatic cancer cells." (PMID 23251334, 2012). "However, comparative genomic hybridization analyses of pancreatic cancer (by this lab and others) did not reveal a significant copy number change of the SOX4 locus (6p22.3)." (PMID 23251334, 2012). "Therefore, it remains to be investigated whether SOX4 interacts with the non-SMAD TGF-β signaling to regulate β-catenin activity for promotion of cell proliferation in pancreatic cancer." (PMID 23251334, 2012).
endometrial cancer (23 papers, 2012 to 2026). Primary or metastatic malignant neoplasm involving the endometrium (mucous membrane that lines the endometrial cavity). "Overexpression of SOX4 in endometrial carcinomas cell lines caused enhancement of beta-catenin/TCF4-driven transcription, whereas cells stably overexpressing SOX4 demonstrated a low proliferation rate, through transactivation of the p21 gene." (PMID 25366337, 2014). "In endometrial cancer, it promotes proliferation and anti-apoptotic effects by sponging miR-363, upregulating SOX4, and activating the PI3K/AKT/GSK-3β pathway." (PMID 40828427, 2025). "Makoto and colleagues have shown that SOX-4 has a positive impact on the β-catenin signal transduction through changes in TCF4 expression during the morular differentiation of endometrial carcinoma cells, thus providing the proliferation arrest." (PMID 34157052, 2021). "We found that single nucleotide polymorphisms (SNPs) in HNF1B, KLF, EIF2AK, CYP19A1, SOX4 and MYC were strongly associated with incident endometrial cancer." (PMID 32066633, 2020). "The associations between endometrial cancer and variants in or around HNF1B, CYP19A1, SOX4, MYC, KLF and EIF2AK found in earlier GWAS were then replicated in the latest and largest GWAS." (PMID 32066633, 2020). "For example, if expression of miR-129-2 is enhanced by epigenetic mechanisms including DNA demethylation and histone acetylation, expression of SRY-related high-mobility group box 4 (SOX4) is suppressed and growth of endometrial cancer is inhibited." (PMID 26535032, 2015). "In endometrial cancer, reactivation of miR-129-2 in cancer cells by pharmacologic induction of histone acetylation and DNA de-methylation resulted in decreased SOX4 expression." (PMID 25344911, 2014). "Epigenetic repression of microRNA-129-2 led to overexpression of SOX4 oncogene in endometrial cancer." (PMID 24194897, 2013). "Furthermore, miR-195 repressed cell metastasis and epithelial-mesenchymal transition by regulating the expression of SOX4 in endometrial carcinoma." (PMID 34258391, 2021). "MiR-129-2-3p targets transcription factor SOX4, which was validated in endometrial cancer." (PMID 24358187, 2013). "In endometrial cancer, NR2F1-AS1 promotes migratory potential by targeting miR-363/SOX4 and activating the PI3K/AKT/GSK-3β pathway." (PMID 40828427, 2025).
non-small cell lung carcinoma (23 papers, 2012 to 2026). A group of at least three distinct histological types of lung cancer, including non-small cell squamous cell carcinoma, adenocarcinoma, and large cell carcinoma. "A study has shown that circRNA THBS1 promotes the migration and invasion of non-small-cell lung cancer cells by adsorbing the expression of miR-129-5p regulating gene SOX4." (PMID 37465349, 2023). "Circ_0005909 promotes cell growth and drug resistance through miRNA-338-3p/SOX4 axis in non-small cell lung cancer." (PMID 37559140, 2023). "circRNA THBS1, a newly discovered circRNA, has been confirmed to regulate non-small-cell lung cancer cells’ functions by sponging miR-129-5p and regulating SOX4 expression." (PMID 37465349, 2023). "Over-expression of SOX4 in human non-small cell carcinoma of lung and urothelial tumor has been reported to result from gene amplification." (PMID 23251334, 2012). "MiR-212 functions as a tumorsuppressor in NSCLC (non-small cell lung cancer) through SOX4." (PMID 40322700, 2025). "Similarly, in non-small cell lung cancer, it enhances cell cycle progression via miR-363-3p/SOX4 signaling." (PMID 40828427, 2025). "SOX4 can strengthen cisplatin-resistance of non-small cell lung cancer cell A549." (PMID 28532536, 2017). "In addition, Sox4 could bind to the promoter regions of DANCR gene to activate DANCR expression, suggesting a positive feedback loop of DANCR/miR-138/Sox4 in non-small-cell lung cancer." (PMID 33123287, 2020). "In non-small cell lung cancer, NR2F1-AS1 enhances migration and invasion through upregulation of SOX4 by targeting miR-363-3p." (PMID 40828427, 2025). "In non-small-cell lung cancer (NSCLC), the downregulation of lncRNA MIR503HG induced by XAV939 may inhibit tumor growth by sponging miR-1273c and regulating SOX4 expression." (PMID 33574983, 2021).
ovarian carcinoma (23 papers, 2013 to 2026). A malignant neoplasm originating from the surface ovarian epithelium. "More importantly, miR-2053/SOX4 axis could be associated with tumour development in ovarian cancer and may be a novel candidate for future targeted treatment for this disease." (PMID 37251541, 2023). "Moreover, biological behaviour changes in ovarian cancer cells caused by miR-2053 inhibitors were strengthened by overexpressed SOX4, whereas the effects of miR-2053 mimics were reversed by transfection with LV-SOX4." (PMID 37251541, 2023). "Our findings revealed the involvement of SOX4 in miR-2053-modulated ovarian cancer cells growth and metastasis, indicating that miR-2053/SOX4 signalling could be associated with the development of ovarian cancer." (PMID 37251541, 2023). "However, low SOX4 expression was significantly associated with poor DFS in ovarian cancer and PCPG." (PMID 37958409, 2023). "Additionally, the alterations in SOX4, such as mutation, amplification, and deep deletion, showed a high percentage in various cancer types, including bladder, prostate, and ovarian cancer datasets, with alteration frequencies of 17%, 16%, and 14%, respectively." (PMID 34442467, 2021). "Our study unveiled the potentiating effects of SOX4/AC093895.1/miR-1253/SOX4 on ovarian cancer cell survival, migration, and invasion." (PMID 41633986, 2026). "Taken together, miR-2053 together with its downstream molecule SOX4 are key regulators of cell proliferation, apoptosis, migration, and invasion in ovarian cancer." (PMID 37251541, 2023). "In summary, these findings revealed the important roles of miR-2053 and its novel target SOX4 in tumourigenesis of ovarian cancer." (PMID 37251541, 2023). "Upregulation of SOX4 was found in ovarian cancer specimens, where its expression was inversely correlated with miR-2053 levels." (PMID 37251541, 2023). "The results imply that in primary ovarian cancer, SOX4 was higher than matched normal fallopian tube (GSE137238) or normal ovarian tissues (GSE66957)." (PMID 34047469, 2021). "Because miR‐92b‐3p expression was lower in the ovarian cancer samples, we also summarized the SOX4 expression in ovarian cancer samples." (PMID 34047469, 2021). "For instance, miR-138 represses ovarian carcinoma cell metastasis via modulating the expressions of SRY-Box Transcription Factor 4 (SOX4) and Hypoxia Inducible Factor 1 Subunit Alpha (HIF-1α)." (PMID 32782028, 2020). "Furthermore, the expression profile of SOX4 was evaluated in clinical samples, and the levels of SOX4 were remarkably elevated in ovarian cancer tissues compared to para-carcinoma controls." (PMID 37251541, 2023). "However, low SOX4 expression was significantly associated with poor OS in HNSC, ovarian cancer, and THYM." (PMID 37958409, 2023). "Moreover, RT-qPCR results revealed the reduction of SOX4 mRNA in ovarian cancer cells following the treatment with miR-2053 mimics." (PMID 37251541, 2023). "In addition, our results revealed that SOX4 is a promising target molecule of miR-2053 in ovarian cancer." (PMID 37251541, 2023). "Moreover, upregulation of SOX4 was detected in ovarian cancer tissues, where its expression levels were negatively correlated with miR-2053." (PMID 37251541, 2023). "Taken together, miR-2053/SOX4 signalling could regulate the proliferation, apoptosis, migration, and invasion of ovarian cancer cells, and this novel pathway may be a candidate target for the optimized treatment of this disease." (PMID 37251541, 2023). "Our data suggested that SOX4 was a novel downstream molecule of miR-2053 in ovarian cancer." (PMID 37251541, 2023). "Furthermore, it was also showed that SNHG12 exerted its carcinogenic effects by interacting with miR-129 and upregulating the expression of SOX4 and thereby promoted ovarian cancer progression." (PMID 33294456, 2020). "Additionally, miR-138-5p regulates SOX4, a determinant of the stemness phenotype, and inhibits invasion in ovarian cancer." (PMID 28423539, 2017).
ovarian carcinoma (continued). "It has been shown that miR-138 may have an effect on tumor metastasis by targeting SOX4 and HIF1a in ovarian cancer and targeting MMP2/MMP9 in cholangiocarcinoma." (PMID 25845814, 2015). "Previous studies indicated that miR-138 may have an effect on tumor metastasis by targeting SOX4 and Hif1a in ovarian cancer, MMP2/MMP9 in cholangiocarcinoma cells and FAK in hela cells." (PMID 24171926, 2013). "Furthermore, SOX4 is involved in miR-2053-regulated growth and metastasis of ovarian cancer cells." (PMID 37251541, 2023). "Moreover, SOX4 was involved in miR-2053-modulated ovarian cancer growth." (PMID 37251541, 2023). "In addition, SOX4 was revealed as a novel target of miR-2053 in ovarian cancer." (PMID 37251541, 2023). "In summary, miR-2053 and its novel target SOX4 could serve essential roles during tumour development of ovarian cancer, more importantly, miR-2053/SOX4 axis may be novel candidate for targeted therapy for patients with ovarian cancer." (PMID 37251541, 2023). "In addition, SOX4 was a putative downstream molecule of miR-2053 in ovarian cancer." (PMID 37251541, 2023). "In addition, SOX4 could be a promising target of miR-2053 in ovarian cancer." (PMID 37251541, 2023). "miR-138 inhibits the occurrence and development of ovarian cancer by downregulating the expression of SOX12 gene and invasion via SOX4 and HIF-1α oncogenic transcriptional factors." (PMID 33673181, 2021). "In ovarian cancer, miR-138 can suppress cell invasion and metastasis by targeting SRY-box 4 (SOX4) and hypoxia inducible factor 1, alpha subunit (HIF-1α)." (PMID 27095063, 2016). "In colorectal and ovarian cancers, miR-138 suppressed cancer cell migration and metastasis through interfered with TWIST2, SOX4 and HIF1-a." (PMID 24941171, 2014).
leukemia (19 papers, 2009 to 2026). A malignant (clonal) hematologic disorder, involving hematopoietic stem cells and characterized by the presence of primitive or atypical myeloid or lymphoid cells in the bone marrow and the blood. "In vivo leukemogenesis assay was performed on Sox4+/+ or Sox4–/– embryos as in A (C) Effects of Bcl2- or Sox4-deficiency on the maintenance of leukemia initiating cells." (PMID 34310280, 2021). "Among these regulons, we were most intrigued by Sox4 because it is implicated in HSC self-renewal and overexpression induces leukemia." (PMID 37838757, 2024). "It should be noted that single gene transduction of MYC and SOX4 induced leukemia by others in different settings, albeit with low penetrance." (PMID 34310280, 2021). "Western blots of MLL-ENL leukemia cells transduced with sgRNA for BCL2 or SOX4 are shown on the left." (PMID 34310280, 2021). "Next, we examined the roles for endogenous BCL2 and SOX4 in maintaining leukemia-initiating cells using a mouse leukemia cell line that we previously established with MLL-ENL." (PMID 34310280, 2021). "CCND2, DNMT3B, SOX4, and IKZF2, all previously reported to associate with leukemia development, were found within the positively correlated genes." (PMID 33597968, 2020). "The overexpression of Sox4 that results from C/EBPα inactivation contributes to the development of a type of leukemia that is characterized by a distinct leukemia-initiating cell phenotype." (PMID 28841206, 2017). "Remarkably, 3 tumors also have insertions in intron 2 of Mef2c, which is a transcription factor oncogene that cooperates with Sox4 in leukemia induction." (PMID 19461887, 2009). "SOX4 is associated with PI3K/AKT and p42-44 MAPK signaling in leukemia." (PMID 39849461, 2025). "Among the HOXA9 target genes, BCL2 and SOX4 synergistically induced leukemia with MYC." (PMID 34310280, 2021). "Endogenous BCL2 and SOX4 support the initiation and maintenance of leukemia." (PMID 34310280, 2021). "Importantly, there was a partial effect of single-gene knockout of Bcl2 and Sox4 on leukemia initiation and maintenance." (PMID 34310280, 2021). "FACS analysis indicated that all of MYC/SOX4-induced leukemias were of myeloid lineage." (PMID 34310280, 2021). "CDK6 was also found to be positively associated with genes identified to contribute to the development of leukemia, including CCND2, DNMT3B, SOX4, and IKZF2, as well as being negatively associated with anticancer microRNAs, including miR-187, miR-9, miR-582, miR708, and miR-362." (PMID 33597968, 2020). "A previous study showed that SOX4 could block differentiation of myeloid leukemia cells through targeting PU.1, and the regulation of PAD4 towards SOX4 further supports the involvement of PAD4 in the differentiation of leukemia." (PMID 26673819, 2016). "Although gene microarray analysis is still needed to fully screen the target genes of PAD4, our study confirms the formation of a functional axis among PAD4, SOX4, and PU.1, which may also represent a promising path for interfering with the abnormal differentiation of leukemia cells." (PMID 26673819, 2016). "Concerning SOX4 and EBF1, it is known that both genes enable the survival signaling of leukemia cells." (PMID 38339034, 2024). "Among the identified regulons, we were most intrigued by that of Sox4, a transcription factor that enhances HSC self-renewal and induces leukemia when overexpressed." (PMID 37838757, 2024). "In the case of MLL fusion-mediated leukemia, MLL fusion proteins directly activate both MYC and HOXA9, while HOXA9 maintains expression of MYC, BCL2, and SOX4, achieving high MYC activity and anti-apoptotic properties simultaneously." (PMID 34310280, 2021). "Methylation also downregulates miR‐129‐2 to induce SOX4, and miR‐143 to upregulate the MLL‐AF4 oncogene in leukemia." (PMID 28179359, 2017). "Here, we assess the roles of the lncRNA CASC15 in regulation of a chromosomally nearby gene, SOX4, and its function in RUNX1/AML translocated leukemia." (PMID 28724437, 2017).
leukemia (continued). "Indeed, co-expression of HOXA9, BCL2, or SOX4 promoted MYC-mediated leukemogenesis, while MYC alone was insufficient to induce leukemia in vivo." (PMID 34310280, 2021). "SOX4 expression is thought to support self-renewal of leukemic cells and to inhibit differentiation in C/EBP α-mutant AML, support PI3K/Akt signaling in BCR-ABL-driven B-ALL, and cooperate with Pu.1 haploinsufficiency in murine leukemia." (PMID 28724437, 2017). "SOX4 also promoted MYC-mediated leukemogenesis in vivo, while neither MYC, BCL2, nor SOX4 alone induced leukemia within 200 days." (PMID 34310280, 2021). "Sox4 deletion also delayed the onset of HOXA9/MEIS1-induced leukemia, although it did not affect MLL-AF10-induced leukemia." (PMID 34310280, 2021).